BRAF (B-Raf proto-oncogene, serine/threonine kinase)
Diseases named in the same sentence as BRAF in open-access papers (continued):
Sharing a sentence is not in itself a finding about the gene and the disease.
colon carcinoma (continued). "We report here that mutant BRAF colon cancer cells are more resistant to AUY922 than those harboring wild-type BRAF due to rapid rebound activation of ERK and Akt." (PMID 27391062, 2016). "On the other hand, treatments with AKT only inhibitor (GDC0941) or MTOR inhibitor (Rapamycin) reduced cell viability in all three treated mutant BRAF colon cancer cell lines in a similar way." (PMID 26802026, 2016). "Regardless, our results clearly demonstrated that CDC37 plays an essential for rebound activation of Akt in mutant BRAF colon cancer cells after treatment with AUY922." (PMID 27391062, 2016). "Treatment with MEK inhibitor PD0325901 had a similar effect on cell viability on all three BRAFV600E colon cancer cell lines, and the same was true for BRAF inhibitor PLX4720." (PMID 26802026, 2016). "In the present study, the role of autophagy in RAS and BRAF induced transformation was examined in colon cancer cell lines." (PMID 26802026, 2016). "Although AUY922 triggered rapid reduction in ERK and Akt activation in both wild-type and mutant BRAF colon cancer cells, activation of ERK and Akt rebounded shortly in the latter leading to resistance of the cells to AUY922-induced apoptosis." (PMID 27391062, 2016). "Consistently, co-treatment with the mutant BRAF inhibitor PLX4720 inhibited reactivation of ERK and sensitized mutant BRAF colon cancer cells to AUY922-induced apoptosis." (PMID 27391062, 2016). "Intriguingly, siRNA knockdown of CDC37 also reduced the basal levels of ERK activation, and inhibited its reactivation, albeit moderately, in mutant BRAF colon cancer cells after treatment with AUY922." (PMID 27391062, 2016). "This appeared to be responsible for resistant of mutant BRAF colon cancer cells to AUY922, in that blockade of ERK or Akt activation pharmacologically or genetically sensitized the cells to AUY922." (PMID 27391062, 2016). "It is conceivable that the inhibitory effect of AUY922 on multiple protein kinases such as CRAF and EGFR would also contribute the combinatorial effect of HSP90 inhibitors and BRAF inhibitors in colon cancer cells." (PMID 27391062, 2016). "Recently, it was suggested that the growth of BRAF-mutant colon carcinoma cell lines can be inhibited by combining a BRAF inhibitor with an EGFR inhibitor, which both were suggested to be inactive as single agents." (PMID 26018524, 2015). "Similar percentages of mutations (40-50%) are found in KRAS and BRAF and 17% of PIK3CA mutations have been determined in colon carcinoma patients." (PMID 25885658, 2015). "It has been reported that colon cancer patients with KRAS and BRAF mutations that lie downstream of epidermal growth factor receptor (EGFR) acquire resistance against therapy with anti-EGFR antibodies, cetuximab and panitumumab." (PMID 25936694, 2015). "A negative feedback loop from ERK to the EGFR has already been proposed previously in colon cancer cell lines with mutant BRAF, where ERK phosphorylation induced the activation of a CDC25C phosphatase, which in turn can dephosphorylate and inhibit the EGFR." (PMID 26065894, 2015). "They will gain recognition in the future as screening test items before drug administration for colon cancer treatment along with BRAF and KRAS." (PMID 25936694, 2015). "Erlotinib resistance in BRAF- and KRAS-mutated colon cancers is clearly reflected in their Raman difference spectra." (PMID 26168967, 2015). "Among two patients with PR, one patient had a BRAF-mutant tumour with multiple liver metastases from an ascending colon cancer." (PMID 26311588, 2015).
colon carcinoma (continued). "The present study revealed that tumour dissemination is less likely to occur in colon cancer patients with MSI and BRAF mutation, whereas the presence of a KRAS mutation increases the likelihood of disseminated disease." (PMID 25884297, 2015). "Our data highlight a distinct escape mechanism by which BRAF-V600E mutant colon cancers escape from Vemurafenib blockade." (PMID 26160848, 2015). "The first case is a 72-year-old male patient who presented initially with stage III KRAS wild-type, BRAF wild-type ascending colon cancer in year 2013." (PMID 26472021, 2015). "KRAS was wild-type in all 4 colon cancer patients but BRAF V600E was detected in two of the 4 cases." (PMID 26375439, 2015). "In this study we find that GNAS mutations associate with a distinct subclass of colon cancers that is typified by location in the proximal colon, by having coincident KRAS or BRAF mutation, and by association with villous morphology." (PMID 24498230, 2014). "In the multivariate analysis, BRAF V600E was an independent prognostic factor for OS in colon cancer, next to sex and TNM." (PMID 25367198, 2014). "We found that the frequencies of BRAF and PIK3CA mutations were significantly lower in rectal than in colon cancer." (PMID 25367198, 2014). "Oncogenic pathways (KRAS/BRAF in colon cancer) circumvent the canonical HH-GLI axis by converging on and further driving GLI to a higher activating state in tumor cells, promoting cellular proliferation, tumor progression and survival." (PMID 24962990, 2014). "Activating mutations in KRAS, and to a lesser extent, its downstream effector BRAF, are frequent events in colon cancer." (PMID 24498230, 2014). "BRAF mutations can abnormally activate downstream signaling pathways in HCC and act as indicator of cetuximab resistance in patients with colon cancer." (PMID 25120700, 2014). "In a study of colon cancer xenografts, there was concordance between gene copy number and mutation (NRAS, KRAS, BRAF, PIK3CA) in first- and second-generation xenografts and in the parent tumor." (PMID 23981300, 2013). "For the BRAF inhibitor AZ628, PIK3CA mutation predicted resistance when it occurred in the context of a breast cancer or colon cancer cell line (training set)." (PMID 23577104, 2013). "Activating BRAF mutations have been associated with high levels of CpG island methylation and MSI in colon cancer." (PMID 23324568, 2013). "The BRAF oncogene mutation is often identified in CIMP-high CRC and is associated with increased cell growth, progression of carcinogenesis, and high colon cancer specific mortality." (PMID 23965959, 2013). "Convincing data on colon carcinoma will be demonstrated at ESMO 2012 with the conclusion to screen patients for BRAFV600E for enrolment in an upcoming clinical trial combining BRAF and EGFR inhibitors." (PMID 23006938, 2012). "They showed that a feedback activation of EGFR occurs in colon cancer cells after BRAF-V600E inhibition very quickly." (PMID 23056577, 2012). "In fact, this feedback activation of EGFR in colon cancer cells leads to a continuous malignant cell proliferation even in the presence of BRAF-V600E inhibition." (PMID 23056577, 2012). "Somatic BRAF mutations, MLH1 methylation and sporadic MSI-H are associated with CIMP-positive (CIMP-high and CIMP-low combined) colon tumors in which the bulk of aberrant methylation can be found." (PMID 20444249, 2010).
colon carcinoma (continued). "OncoCarta assays interrogate 99%, 98%, and 78% of the known colon cancer mutations in BRAF, KRAS, and PIK3CA, respectively, based on a large number of colon cancer samples that have been sequenced in BRAF (n = 4628), KRAS (n = 858) and PIK3CA (n = 247)." (PMID 20233444, 2010). "To decipher the possible genetic reasons underlying the high incidence of colon cancer in AAs, we earlier conducted studies on the MSI, methylation of CAN genes and mutations of known genes such as BRAF and KRAS." (PMID 20126641, 2010). "While HCT116 harbors mutant KRAS, HT29 colon cancer cells are wildtype for KRAS but harbor mutant BRAF." (PMID 21129190, 2010). "In HCT116, a colon cancer line, that carries a mutant KRAS allele, we find that interfering with the RAF effector axis at the level of RAF (BRAF and CRAF) and MEK (MEK1 and MEK2) was effective in delaying tumor growth." (PMID 19492075, 2009). "We specifically chose the human colon carcinoma cell lines SW480 (which harbors a KRAS mutation like HCT116) and HT-29 (harboring a BRAF mutation)." (PMID 19014680, 2008). "By exploring such approaches, we may identify new treatment options for patients with BRAF-V600E mutant colon cancer." (PMID 40678543, 2025). "When adjusted for standard of care (ESCAT I‐II) genes (i.e., PIK3CA, ESR1, and ERBB2 for breast cancer; KRAS, NRAS, and BRAF for colon cancer, etc.), 37 (3.6%), 0 (0%), 1 (0.2%), and 0 (0%) of mutant alleles would have been negative among breast, bowel, lung, and skin cancer samples, respectively." (PMID 40056420, 2025). "Among nine subgroups defined according to primary tumour location and RAS-, and BRAF-V600E status, metastasectomy rates were the lowest among patients with BRAF-V600Emt right colon tumours (12%) and the highest among patients with RAS&BRAFwt rectal tumours (42%)." (PMID 40437037, 2025). "Among nine subgroups defined according to primary tumour location, and RAS- and BRAF-status, mOS after metastasectomy was the shortest among patients with BRAF-V600Emt right colon cancers (29 months) and the longest among patients with RAS&BRAFwt rectal cancers (95 months)." (PMID 40437037, 2025). "The PETACC-3 study, which analyzed BRAF and KRAS mutations in 1,404 colon cancer patients, demonstrating that patients with the BRAF mutation had inferior OS compared to those with the wild type, and the contrast was more pronounced when stratified by microsatellite instability (MSI)." (PMID 41034734, 2025). "However, genetic silencing of the gene encoding MEK2 using short hairpin RNAs inhibits the proliferation of human colon carcinoma cell lines HCT116 and HT29, which harbor mutations in KRAS and BRAF." (PMID 38277448, 2024). "Molecular mechanisms may account for the differences in CSS for RSCC and LSCC, as microsatellite instability (MSI), BRAF mutations, and RAS mutations have established predictive and prognostic genetic markers for colon cancer." (PMID 38651190, 2024). "BRAF mutation, especially the V600E subtype, is associated with worse survival in MSS colon cancer." (PMID 39253758, 2024). "In addition, inhibition or knockout of PTPN11 confers sensitivity to BRAF inhibition in BRAF mutant colon cancer." (PMID 38504984, 2024).
colon carcinoma (continued). "Similar results have been demonstrated in primary colon cancers, showing that the CT based-radiomics signature was significantly associated with KRAS/NRAS/BRAF mutations and this approach may be useful for analysis of tumor genotype." (PMID 39329997, 2024). "Consequently, we identified male sex, age ≥50, colon tumors, early-stage tumors, NRAS mutant tumors, and BRAF wild-type tumors as independent risk factors for synchronous high-risk polyps." (PMID 38978992, 2024). "Moreover, our data indicated that the hypermethylated CEACAM5 group showed molecular pathological features with a BRAF mutation, TGFB2 mutation, MSI‐H, and proximally located colon tumors that were similar to CMS1 tumors." (PMID 37942534, 2024). "In addition, right-sided colon tumors, which have increased prevalence of KRAS and BRAF mutations and are associated with worse prognosis compared to left-sided colon tumors, respond poorly to EGFR inhibition." (PMID 38672633, 2024). "This could be due to differences in the molecular subtypes of colon cancer (e.g., RAS mutation, BRAF mutation and microsatellite instability status)." (PMID 38243170, 2024). "Colon cancer cell lines showed increased resistance to cetuximab when PTEN expression is lost or PIK3CA is mutated, and an even higher degree of resistance when any of these alterations is concurrently present with RAS/BRAF mutations." (PMID 38731914, 2024). "The remaining patients were patients with right or left colon tumors and we compared the overall survival (OS), molecular mutations (KRAS, NRAS, BRAF, MSI status), and clinicopathological features of our patients with transverse colon tumors with these patients." (PMID 39629291, 2024). "However, in many clinical trials including BRAF V600E-mutated CRC treatment, rectal cancer was often grouped with left-sided colon cancer for analysis." (PMID 39464719, 2024). "This systematic review aims to investigate how the presence of NRAS, KRAS, or BRAF mutation in non-metastatic MSI colon cancer patients affects outcomes such as DFS, OS, and survival after recurrence (SAR)." (PMID 38786299, 2024). "Future studies using organoid models in conjunction with in vivo studies could help further address the differential dependencies for proximal vs. distal colon cancer development, as well as for KRAS and BRAF mutation-driven tumorigenesis." (PMID 38360902, 2024). "This systematic review synthesizes a comprehensive range of studies examining the prognostic significance of NRAS, KRAS, and BRAF mutations within non-metastatic MSI colon cancer." (PMID 38786299, 2024). "Data indicates that constitutive activation of BRAF may increase the migratory and invasive capacity of human colon cancer cells." (PMID 35642343, 2023). "Treatment options for advanced colon cancer should be stratified based on various factors, including the location of the primary lesion, microsatellite and mismatch repair status, and the presence of RAS and BRAF gene mutations." (PMID 37741975, 2023). "In this respect, ezrin inhibitors might be further investigated within pre-clinical and clinical set-ups as an adjunct to BRAF inhibitors in treating BRAFV600E-mutant colon cancer." (PMID 37629086, 2023). "The authors also identified that colon cancers with BRAF mutant had higher stromal score (P = 0.02), immune score (P < 0.0001), ESTIMATE (Estimation of STromal and Immune cells in MAlignant Tumour tissues using Expression data) score (P = 0.0001), and lower tumor purity (P = 0.0003)." (PMID 37302081, 2023). "These alterations were detected in 9 NSCLC samples (2 ALK rearrangements and 5 EGFR mutations, 1 BRAF mutation, and 1 G12C/KRAS mutation); 7 breast cancer samples (7 HER2 amplifications); 5 colon cancer samples (5 KRAS mutations); and 3 gastric cancer samples (2 MSI-high and 1 HER2 amplification)." (PMID 36832270, 2023).
colon carcinoma (continued). "After patient file verification and proofreading, this patient had two distinct metachronous primary colon cancers, a dMMR/MSI, BRAF-mutated and hypermethylated MLH1 promoter, right colon cancer in 2005, and in 2003 a pMMR/MSS, BRAF wild-type, left-sided colon cancer stage II treated by surgery." (PMID 35457245, 2022). "Interestingly, specific repression of Furin in colon tumors induced by cancer cells with KRAS or BRAF mutation inhibited the expression of Nanog and LGR5 compared to wild-type KRAS and BRAF developed tumors." (PMID 35267511, 2022). "BRAF inhibition in the early stages of colon cancer may be considered a new therapeutic target in those patients." (PMID 35592200, 2022). "Studies have reported that BRAF mutations and KRAS mutations are independent and exclusive of each other, account for 5–15% of metastatic colon cancers, and are associated with poor prognosis in advanced colon cancer." (PMID 35479956, 2022). "Reactivation of ERK and AKT has been shown to drive drug resistance to AUY922 in BRAF mutated colon cancer and to STA-9090 in KRAS-mutant non-small cell lung cancer." (PMID 35327426, 2022). "Stabilization of Akt in mutant BRAF colon cancer requires both Hsp90 and CDC37." (PMID 36012578, 2022). "A cohort of 53 patients with actionable lesions was identified via in-house panel sequencing (n = 34) or, especially in patients with colon cancer, by targeted sequencing of hotspot regions (such as BRAF) as well as testing for microsatellite stability or PDL-1 expression (n = 19)." (PMID 34436668, 2022). "show that BRAF V600E mutation may induce the expression of PD-L1 and then increase chemotherapy-induced apoptosis by inducing BIM and BIK proteins in colon cancer." (PMID 35619907, 2022). "Previously, Furin inactivation was found to impair the malignant phenotype of colon cancer cells with activating KRAS or BRAF mutations but not with wild-type (WT) KRAS or BRAF." (PMID 35267511, 2022). "To evaluate the effect of Furin repression on the expression of the main Ca2+ regulators previously reported to be involved in colon cancer, we directly analyzed their expression in colon cancer cells with or without KRAS or BRAF mutation." (PMID 35267511, 2022). "Notably, the proportion of patients with BRAF mutations in this study is relatively high, and these patients are not known to have MSI-H; interestingly, most of them have left-sided colon tumours." (PMID 35864467, 2022). "Baseline expression levels of selected protein targets were investigated by western blot in two BRAFV600E mutant colon cancer cell lines harboring WT KRAS (HT-29 and RKO), two WT BRAF cell lines carrying KRAS mutations (HCT 116 and SW480) and a double WT colon cancer cell line (Caco-2)." (PMID 34201061, 2021). "The BRAF mutation accounts for around 10% cases of colon cancer and serves as a strong negative prognostic marker for patients." (PMID 34381786, 2021). "It has previously been shown that BRAF mutated RKO colon cancer cells have remarkably higher activities and protein expression levels of SphK1 and SphK2 in comparison to several other colon cancer cell lines harbouring wild-type BRAF, and that they exhibit the least sensitivity to oxaliplatin." (PMID 34639107, 2021). "BRAF and DPYD mutations can be used as markers to guide treatment in colon cancer." (PMID 34594379, 2021). "Importantly, BRAF mutant colon cancer cell line HT-29, with acquired resistance to vemurafenib, displayed an increased expression of activated AKT." (PMID 34639107, 2021). "In addition, the combination of ERK inhibitor U0126 and CYP inhibitor induced a much higher inhibitory effect on ERK activity in colon cancer cells with BRAF mutant." (PMID 34037092, 2021). "With this in mind, inhibition of actin remodeling could also prove to be a promising strategy to overcome resistance to vemurafenib in BRAF mutant colon cancer." (PMID 34201061, 2021).